PLAUR (plasminogen activator, urokinase receptor)
Description:
GPI-anchored receptor that recruits and activates the urokinase-type plasminogen activator (uPA) at the cell surface. Activated uPA converts plasminogen into plasmin, initiating extracellular matrix degradation and remodeling. Also binds the extracellular matrix protein vitronectin, promoting cell-matrix adhesion and indirectly integrin signaling. This dual interaction coordinates dynamic changes in cell migration, proliferation, and tissue remodeling.
Synonyms: U-PAR; uPAR; CD87; URKR
Tractability: Small molecule: a structure with a bound ligand is known; it belongs to a druggable protein family. Antibody: UniProt places it where antibodies can reach, with high confidence; its Gene Ontology location is reachable by antibodies, with high confidence; UniProt predicts a signal peptide or a membrane-spanning region; the Human Protein Atlas places it where antibodies can reach. PROTAC: ubiquitination databases record sites on it; its protein half-life has been measured; a small molecule that binds it is known.
Target class: Membrane receptor
Gene: Protein-coding gene on chromosome 19 (43,646,095 to 43,670,547, reverse strand). Ensembl gene ENSG00000011422.
Subcellular location: Cell membrane (Isoform 1); Cell projection, invadopodium membrane; Secreted (Isoform 2)
Subcellular location (Human Protein Atlas): Plasma membrane
Pathways (Reactome):
Immune System: FXIIa activates plasma kallikrein-kinin system; Neutrophil degranulation; Regulation of FXIIa and plasma kallikrein activity
Hemostasis: Dissolution of Fibrin Clot
Metabolism of proteins: Attachment of GPI anchor to uPAR
Gene Ontology:
Molecular function: cell-matrix adhesion mediator activity; enzyme activator activity; enzyme binding; protein binding; protein domain specific binding; signaling receptor binding; urokinase plasminogen activator receptor activity; signaling receptor activity
Biological process: cell-matrix adhesion; negative regulation of apoptotic process; negative regulation of intrinsic apoptotic signaling pathway; plasminogen activation; positive regulation of DNA binding; positive regulation of epidermal growth factor receptor signaling pathway; positive regulation of extracellular matrix disassembly; positive regulation of homotypic cell-cell adhesion; positive regulation of protein phosphorylation; positive regulation of release of cytochrome c from mitochondria; protein localization to cell surface; regulation of cell adhesion; blood coagulation; chemotaxis; regulation of fibrinolysis; regulation of plasminogen activation; regulation of proteolysis; signal transduction; urokinase plasminogen activator signaling pathway
Cellular component: cell surface; focal adhesion; plasma membrane; protein complex involved in cell-matrix adhesion; serine-type endopeptidase complex; endoplasmic reticulum lumen; endoplasmic reticulum membrane; external side of plasma membrane; extracellular region; extrinsic component of membrane; membrane; specific granule membrane
Genetic constraint (gnomAD): Loss-of-function variants: 20 observed, 31.89 expected, observed/expected ratio (o/e) 0.63, 90% interval 0.44 to 0.91. The upper end of that interval is the gene's LOEUF score, 0.91, which puts it in group 3 of 6, group 1 being the genes least tolerant of losing a copy. Missense variants: 403 observed, 449.54 expected, observed/expected ratio (o/e) 0.9, 90% interval 0.82 to 0.97. Synonymous variants: 147 observed, 174.98 expected, observed/expected ratio (o/e) 0.84, 90% interval 0.73 to 0.96.
Homologues: Orthologues: chimpanzee PLAUR (99% identical), macaque PLAUR (82% identical), pig PLAUR (67% identical), rabbit PLAUR (62% identical), mouse Plaur (61% identical), rat Plaur (61% identical), guinea pig PLAUR (58% identical). Paralogues in human: LYPD3 (20% identical), LYPD5 (15% identical).
Diseases named in the same sentence as PLAUR in open-access papers:
PLAUR is named in the same sentence as 336 diseases in open-access papers, as found by Europe PMC text mining. Sharing a sentence is not in itself a finding about the gene and the disease. The quoted sentences say what the papers report.
breast carcinoma (150 papers, 1998 to 2026). "Hypomethylation of the PLAUR gene promoter has been linked to increased uPAR expression in cancers such as colorectal and breast cancers, where it correlates with enhanced metastatic potential and poor prognosis." (PMID 41154366, 2025). "Here we find 40 proteins associated with common cancers, such as PLAUR and risk of breast cancer [odds ratio per standard deviation increment: 2.27, 1.88-2.74], and with high-mortality cancers, such as CTRB1 and pancreatic cancer [0.79, 0.73-0.85]." (PMID 38684708, 2024). "In summary, macrophages were the major immune cells in breast adipose tissue and breast cancer leads to a marked increase in the proportion of MARCO+PLAUR+ and lipid-associated macrophages." (PMID 37153595, 2023). "Furthermore, PLAUR gene polymorphism also affects the prognosis of tumours, with SNPs in the gene found to be associated with disease-free survival in breast cancer." (PMID 37469404, 2023). "Taken together, our analysis of different publicly available breast cancer datasets independently demonstrates that higher PLAUR expression is associated with increased aggressiveness of breast cancer and that all types of breast cancer express higher levels of uPAR than normal breast tissue." (PMID 32337090, 2020). "We previously demonstrated that uPAR promotes EMT in hypoxic breast cancer cells and, inversely, that PLAUR gene-silencing induces mesenchymal-epithelial transition." (PMID 40759369, 2025). "The gene mapping of 24 DEGs through PubMed, OMIM, MeSH, and PMC databases provided eight significant breast cancer associated genes: ID4, NCOA1, RHEB, PDZK1, PLAUR, AKC1R2, ANXA1 and SLIPI." (PMID 33593445, 2021). "Database analyses showed that the expression of the gene encoding uPAR (PLAUR) is observed in the luminal, HER2+, and triple-negative subtypes of breast cancer, and that expression is higher in the subtypes where metastatic recurrence is fastest." (PMID 32337090, 2020). "PLAUR expression was increased in the breast cancer subtypes that have historically demonstrated the shortest median time to recurrence, where the highest expression is seen in the triple-negative subtype." (PMID 32337090, 2020). "Nevertheless, such cooperativity of HER2 and PLAUR suggests the importance of simultaneous targeting of both Her2 and uPAR in breast cancer patients." (PMID 29484286, 2018). "To identify the common transcription factors that have propensity to regulate both HER2 and PLAUR gene expression in HER2-positive breast carcinoma, we submitted their gene symbols into GEMS launcher software." (PMID 25897424, 2015). "We also observed an increase in the expression of additional target genes of the pathway, namely, c-Jun, VEGFA and PLAUR in TN breast cancer cell lines." (PMID 24143235, 2013). "Additionally, replication in UKBB and Finngen was observed for other results, including PLAUR [breast cancer OR: 1.82, 95% CI: 1.37 to 2.42], POGLUT3 [kidney cancer OR: 0.72, 95% CI: 0.60 to 0.88], and CTRB1 [pancreas cancer OR: 0.83, 95% CI: 0.75 to 0.92]." (PMID 38684708, 2024). "Furthermore, PLAUR was highly expressed in breast cancer tissues compared with matched TCGA normal mammary tissues (Log2FC > 1, p < 0.01)." (PMID 37345070, 2023). "There was significant upregulation of PLAUR in lung and colon cancer compared to breast cancer." (PMID 36124441, 2023). "Furthermore, hypoxia results in increased expression of plasminogen activator urokinase receptor (PLAUR) via HIF-1α expression in breast cancer." (PMID 36140753, 2022). "Therefore, upregulation of HER2 and PLAUR by common oncogenic players can be attributed as being specific to an early-stage aggressive breast carcinoma subtype." (PMID 25897424, 2015). "Indeed, increased levels of PLAUR and SERPINE1 have been associated with poor prognosis in breast cancer patients." (PMID 20840765, 2010). "Research has shown that the PLAUR gene plays a role in PTC differentiation and HER2-positive breast cancer metastasis." (PMID 40535127, 2025).
breast carcinoma (continued). "The current data identified the high level of MARCO+PLAUR+ macrophages in adipose tissue adjacent to tumors at single cell level, indicating MARCO+PLAUR+ macrophages were related to the progression of breast cancer." (PMID 37153595, 2023). "In addition, it has been shown that wild-type and exon 4/5-deleted PLAUR mRNA transcript variants are predictive of disease metastasis free survival and overall survival in breast cancer patients, but do not hold predictive significance for PFS and overall survival in ovarian cancer patients." (PMID 36124441, 2023). "PLAUR expression has been found in aggressive breast cancers such as in TNBC, a subset of Her2 positive breast cancer, and in tamoxifen refractory breast cancer." (PMID 36009568, 2022). "We took as «baits» five bimodal genes reported as important breast cancer genetic markers - ERBB2, ESR1, PLAUR, FN1, and STAT1, and calculated the "close neighbor" gene groups that were synchronously expressed with each of them in the Sorlie295 set." (PMID 20158879, 2010). "We therefore developed a new macrophage-specific SPP1 TAM signature (PLAUR, SLC11A1, BRI3, FBP1, C15orf48) using publicly available scRNA-Seq data from lung, colorectal and breast cancers and validated the signature using multiple independently published scRNA-Seq datasets." (PMID 41415295, 2025).
glioma (71 papers, 2010 to 2026). A benign or malignant brain and spinal cord tumor that arises from glial cells (astrocytes, oligodendrocytes, ependymal cells). "Functional enrichment analysis and GSVA analysis demonstrated that PLAUR was associated with the MES phenotype of glioma and the hypoxia-immunosuppression-related microenvironmental components." (PMID 38398231, 2024). "Single-cell sequencing analysis revealed that PLAUR mediated the ligand–receptor interaction between tumor-associated macrophages (TAMs) and glioma cells." (PMID 38398231, 2024). "The overexpression of PLAUR has been shown to be associated with poor prognosis in many types of gliomas, particularly in mesenchymal subtype GBM and LGG." (PMID 35800363, 2022). "The expression of S100A4, EMP3, and PLAUR was increased in recurrent gliomas compared with primary gliomas as were the risk scores of recurrent gliomas." (PMID 35574375, 2022). "PLAUR is associated with the malignancy and M2 macrophage infiltration of glioma and acts as an unfavorable prognostic predictor, and the association of PLAUR expression with macrophage infiltration is not limited to tumors." (PMID 35111196, 2021). "High mRNA expression of PLAU (HR=1.578, 95%CI 1.208-2.061, p=0.0008) and PLAUR(HR=1.38, 95%CI 1.05-1.814, p=0.0211) were independently associated with significantly shorter OS of glioma patients." (PMID 35087738, 2021). "In conclusion, our current study indicated that overexpression of PLAU and PLAUR is associated with poor prognosis in primary and recurrent glioma patients, especially in LGG." (PMID 35087738, 2021). "PLAUR has also been implicated in Glioma and is suggested to play roles in immunosuppression." (PMID 39115871, 2024). "Multiple studies have shown that PLAU and PLAUR are highly expressed in gliomas and promote glioma cell invasion, tumor growth, and angiogenesis." (PMID 40224547, 2025). "The IHC staining for the PLAUR protein using tissue sections from glioma patients validated the bioinformatic result." (PMID 38398231, 2024). "In summary, the single-cell analysis revealed that PLAUR was expressed predominantly in both MES-like glioma cells and macrophages, contributing to the heterogeneity of GBM." (PMID 38398231, 2024). "Following the knockdown of PLAUR in glioma cells, the decreased expression of CD44 and vimentin was detected by Western blotting, while the overexpression of PLAUR via a plasmid was shown to elevate the protein level." (PMID 38398231, 2024). "This group of macrophages also expressed higher levels of PLAUR (Plasminogen Activator Urokinase Receptor) which links with increased macrophage infiltration and poor prognosis in gliomas." (PMID 38480935, 2024). "To investigate the association between PLAUR in macrophages and the mediation of MES transition in glioma cells with OSM or ICAM1, we assessed the mRNA expression of OSM and ICAM1 in THP1-derived macrophages following lentiviral shPLAUR or shNT transfection." (PMID 38398231, 2024). "Future work should address these issues so that we can better understand how PLAUR participates in glioma’s acquisition of the MES phenotype." (PMID 38398231, 2024). "A study recently found that the infiltration level of CD8+ T-Cells decreased while that of macrophages increased along with the increase of PLAUR expression in glioma samples." (PMID 36425564, 2022). "Overexpression of PLAU and PLAUR is regarded as independent prognostic factors for shorter OS of glioma patients through Cox regression analysis." (PMID 35087738, 2021). "Significant changes of PLAU and PLAUR expression in transcription level between glioma and normal brain tissues (ONCOMINE)." (PMID 35087738, 2021). "Fifth, it is hard to know how PLAU and PLAUR expression can be involved in the glioma formation, or their expression is a consequence of the glioma development." (PMID 35087738, 2021). "With regard to the survival analysis, there is high mRNA level of PLAU/PLAUR in primary and recurrent gliomas as a whole." (PMID 35087738, 2021).
glioma (continued). "High expression of PLAU and PLAUR predicted a poor prognosis in primary glioma and recurrent glioma patients, especially in lower grade gliomas." (PMID 35087738, 2021). "Cox regression analysis indicated that high expression of PLAU and PLAUR were independent prognostic factors for shorter overall survival in glioma patients." (PMID 35087738, 2021). "This study aims to evaluate the prognostic value of PLAU/PLAUR transcription expression in glioma and to explore how these pairs of genes affect the generation and progression of glioma." (PMID 35087738, 2021). "PLAU and PLAUR transcriptional expressions are found significantly higher in glioma compared with normal brain tissue, and are more obvious in high-grade gliomas." (PMID 35087738, 2021). "This study aims to evaluate the prognostic value of PLAU/PLAUR transcription expression in glioma and to explore how they affect the generation and progression of glioma." (PMID 35087738, 2021). "Of these, ten genes (CTSZ, EFEMP2, ITGA5, KDELR2, MDK, MICALL2, MAP 2 K3, PLAUR, SERPINE1 and SOCS3) can potentially classify patients with gliomas into different risk groups." (PMID 32878880, 2020). "Herein, we show that patient survival correlates inversely with PLAUR mRNA expression in gliomas of all grades, in glioblastomas, and in the subset of glioblastomas that demonstrate the mesenchymal gene expression signature." (PMID 29445239, 2018). "Furthermore, PLAUR demonstrates heterogenous expression in TAMs and glioma cells, mediating the MES phenotype through cell-to-cell interaction." (PMID 38398231, 2024). "Increased expression of PLAUR indicated an unfavorable prognosis in glioma." (PMID 38430429, 2024). "PLAUR, a widely studied oncogenic molecule, promotes tumor progression by regulating biological processes, such as cell proliferation and adhesion, in various tumors, including gliomas." (PMID 38398231, 2024). "In our study, we elucidated the association between PLAUR and the MES phenotype and further investigated whether the differential expression of PLAUR in TAMs contributed to MES glioma’s phenotype acquisition through modulating cell-to-cell interactions." (PMID 38398231, 2024). "Our findings indicate that PLAUR regulates both glioma cells and tumor cell-extrinsic factors that favor the MES phenotype and suggest that PLAUR might be a potential target for GBM therapy." (PMID 38398231, 2024). "Cumulatively, TAMs exhibiting heightened PLAUR expression demonstrated enhanced potential to drive the MES phenotype of glioma; various ligand–receptor pairs may be involved in this expression." (PMID 38398231, 2024). "In the intricate landscape of glioma pathogenesis, the elucidation of risk scores derived from pivotal hub genes—RPL3, RPL12, PTEN, IFNGR2, KLF10, PLAUR, MSN, and IKBIP—emerged as a critical component in understanding the disease’s progression and patient stratification." (PMID 38137116, 2023). "Likewise, the gene plasminogen activator urokinase receptor (PLAUR) which has been linked to extracellular matrix (ECM) degradation in a multitude of tumors, has been identified as an immunological biomarker in glioma." (PMID 36425564, 2022). "Inhibition of expression of PLAU/PLAUR might blockade these crucial cancer-related pathways, and plays an anti-tumor role in gliomas." (PMID 35087738, 2021). "However, high expression of PLAU and PLAUR indicated shorter OS in patients with current gliomas of WHO grade III (p=0.0041, p=0.00079 respectively)." (PMID 35087738, 2021). "Previous studies have shown that PLAUR was involved in cancer cell migration, invasion and metastasis processing and could predict the prognosis of many cancers, such as glioma and oral squamous cell carcinoma." (PMID 35141153, 2021). "First, though some recurrent gliomas are found with high expression of PLAU and PLAUR that predict poor prognosis, it is unknown whether the two genes are involved in the recurrence of glioma." (PMID 35087738, 2021).